WNT5A (Wnt family member 5A)
Diseases named in the same sentence as WNT5A in open-access papers (continued):
Sharing a sentence is not in itself a finding about the gene and the disease.
glioma (continued). "Therefore, this study indicated that circKIF4A acts as a ceRNA to active Wnt5a/β-catenin signaling pathway mediated glioma progression by depressing miR-139-3p expression." (PMID 32268875, 2020). "Furthermore, it is very important to explore WNT5A promoting glioma development through the WNT/Ca+ pathway in glioma more clearly." (PMID 32181818, 2020). "Additionally, immunohistochemical experiments showed that the expression of Wnt5a was increased significantly and located mainly in the cytoplasm or extracellular in glioma tissues." (PMID 32268875, 2020). "For WNT5A, significantly higher mRNA expression of WNT5A in glioma was observed compared with NB." (PMID 32181818, 2020). "Therefore, the interaction of circKIF4A, miR-139-3p and Wnt5a in glioma is worthy of our comprehensive investigation." (PMID 32268875, 2020). "WNT5A was differentially higher expressed in glioma cell lines among 19 WNTs, implying that WNT5A might play distinct functions in glioma." (PMID 32181818, 2020). "We reported that miR-129-5p directly targeted Wnt5a in glioma." (PMID 29531296, 2018). "While Wnt5a has indeed been shown to be overexpressed in GBM cells and has been implicated in modulating their migratory and proliferative abilities, these studies were conducted in immortalized glioma cell lines in vitro." (PMID 28821904, 2018). "We also confirmed the correlation between the expression profile of miR-129-5p and Wnt5a in glioma patients from the Chinese Glioma Genome Atlas (CGGA) and investigated the overall survival of GBM patients using two data sets, namely, TCGA and GSE16011, according to their Wnt5a expression status." (PMID 29531296, 2018). "Moreover, silencing the expression of Wnt-2, Wnt-5a, and Fz-2 in the U251 glioma cell line decreases invasion." (PMID 22400111, 2012). "Targeting low taurine synthesis or modulating Wnt5a promoter methylation may be a novel therapeutic strategy for the treatment of gliomas, and inhibitors of low taurine synthesis have the potential to reduce glioma cell invasion by altering the epigenetic regulation of Wnt5a." (PMID 40373156, 2025). "Classical WNT pathway activation may be associated with an increase of WNT5A, but there is no literature reporting WNT5A is the main factor of classic classical pathway activation in glioma." (PMID 32181818, 2020). "Furthermore, the expression of WNT5A and WNT10B was associated with the clinicopathology of glioma." (PMID 32181818, 2020). "Finally, Go and KEGG analysis revealed WNT5A was associated with multiple signal translations, and crucial oncogenes (EGFR and MDM2) and 2 important tumor suppressors (PTEN and IKN4a/ARF) were found closely correlated with WNT5A in glioma." (PMID 32181818, 2020). "In addition, RYK, an atypical member of the receptor tyrosine kinase (RTK) family involved in the control of neuronal differentiation, resulted to be essential for WNT5a-dependent invasiveness in glioma, and its expression correlated with the WHO histological classification for glioma tissues." (PMID 29462960, 2018). "Myeloid/microglial cells can communicate with MAN1C1-expressing glioma cells via signals produced (SPP1, GRN, PSAP, HBEGF, LGALS9, WNT5A)." (PMID 39333557, 2024). "In the same time, miR-155, miR-410, and miR-181a/b correlated negatively with WNT5A, MET, and EGFR in plasma of high-grade glioma patients." (PMID 35646622, 2022). "Latest reports have shown that these miRNAs by regulation PDCD4, WNT5A, MET, and EGFR also serves certain biological function in the progression of various human tumors including glioma." (PMID 35646622, 2022). "Hsa-miR-129-5p, a tumor suppressor, is down-regulated in gliomas and inhibits glioma proliferation, migration and development by targeting TGIF2, WNT5A, DNMT3A, HOXC10, FNDC3B." (PMID 35601497, 2022). "The GO enrichment analysis was then performed to determine the function of WNT5A and WNT10B with neighbor genes in glioma using DAVID." (PMID 32181818, 2020).
glioma (continued). "To understand the function and molecular mechanism of WNT5A and WNT10B in glioma, we performed PPI network, GO and KEGG analyses." (PMID 32181818, 2020). "Although our study provided important insights into the prognostic and research values of WNT5A and WNT10B in glioma patients at the mRNA level, there still are some limitations to the present study." (PMID 32181818, 2020). "For CNS tumor, higher expression of WNT5A, lower expression of WNT7A and lower expression of WNT10B were found in glioma compared with NB tissues." (PMID 32181818, 2020). "Then, qRT-PCR was used to monitor the expressions of circKIF4A, miR-139-3p and Wnt5a in NHA and four glioma cell lines (A172, SHG44, U251 and LN229)." (PMID 32268875, 2020). "On the other hand, though we performed analysis to predict the mechanism and biofunction of WNT5A and WNT10B in glioma, a remarkable amount of work is urgent to investigate the distinct role of WNTs in glioma." (PMID 32181818, 2020). "Although aberrant expression or upregulation of Wnt5a has been associated with increased tumor cell invasion and metastasis across several different solid cancers, its role in the regulation of the invasive properties and progression of high-grade gliomas has not been fully delineated." (PMID 28821904, 2018). "In glioma cell culture, additional administration of WNT5A, WNT3A and WNT1 promoted cell proliferation, which is in line with the clinical report that high expression of WNT5A, WNT3A and WNT1 correlated with short OS of patients with gliomas." (PMID 41184253, 2025). "Research has shown that Wnt5a, a non-canonical Wnt ligand, appears to be a critical master regulator of the invasive capacity of human glioma stem cells (GSCs) in vivo." (PMID 36675073, 2023). "Furthermore, the overexpression of WNT5A and WNT16 correlated with worse overall survival in glioma patients, whereas high expression of WNT5B, WNT10B, and WNT3 correlated with better overall survival probability." (PMID 36814601, 2023). "Go analysis predicted that WNT5A regulated molecular functions including GTPase activity, biological processes such as signal translation, and biological pathways such as EGFR-dependent signaling events in glioma." (PMID 32181818, 2020). "KEGG pathway analysis also showed that the neighbor genes of WNT5A were widely distributed in multiple pathways in the de novo pathways of glioma occurrence, in which crucial oncogenes (EGFR and MDM2) and 2 important tumor suppressors (PTEN and IKN4a/ARF) were closely correlated with WNT5A." (PMID 32181818, 2020). "The study also indicated that WNT5A can serve as a candidate to diagnose and therapy glioma, while WNT10B might be valuable for anti-glioma research." (PMID 32181818, 2020). "Wnt5a is an independent predictor of poor prognosis in GBM19,20, which accounts for ~40% of glioma." (PMID 29531296, 2018). "Inhibition of Wnt3a, but not Wnt4 or Wnt5a, attenuated cell growth and neural sphere formation in these PN glioma spheres." (PMID 27698350, 2016). "Noncanonical Wnt-5a, which signals through β-catenin independent pathways (including the planar cell polarity and the calcium pathways), enhances the migration of glioma cells by regulating the expression of MMP-2." (PMID 22400111, 2012). "Combination EA35TMZ320 reduced the transcription of WNT5A, an upstream intracellular member known to play a pro-tumor role in glioma to induce the migration of GBM cells to increase cell proliferation and to correlate with higher WHO histological glioma classification grades." (PMID 41031155, 2025). "In addition, WNT5A was positively correlated and WNT10B inversely correlated with glioma grade." (PMID 36814601, 2023). "Consequently, the expression of circulating miR-155, miR-410, and miR-181a/b and its putative gene-targets PDCD4, WNT5A, MET, and EGFR had a strong inverse relation in high-grade glioma, thereby suggesting that the potential roles of miR-155, miR-410, and miR-181a/b in oncogenesis of glioma tumors." (PMID 35646622, 2022).
glioma (continued). "Moreover, miR-155, miR-181a/b and miR-410 may participate in the molecular mechanism of high-grade glioma by interaction PDCD4, WNT5A, MET, and EGFR." (PMID 35646622, 2022). "Analyzing the mRNA data of 19 WNTs from TCGA and CGGA database, we found that WNT5A mRNA expression level was significantly correlated with the grade of glioma in both TCGA and CGGA databases; however, WNT10B expression was inversely correlated with the grade of glioma." (PMID 32181818, 2020). "Our study found a negative correlation between miR-139-3p and Wnt5a levels in glioma samples." (PMID 32268875, 2020). "Moreover, expression of noncanonical Wnt-5a is also upregulated in high grade gliomas, in which Wnt-5a stimulates cell proliferation." (PMID 22400111, 2012). "Overall, the mRNA levels of ACVR1, STAT3, WNT5A, KLF4 and DMC1 were obviously decreased in glioma samples with 1p19q codeletion compared to those in glioma samples without 1p19q codeletion." (PMID 36435765, 2022). "However, the enhanced glioma proliferation induced by WNT3A, but not by WNT5A or WNT1, was diminished by CELSR2 silencing." (PMID 41184253, 2025).
pancreatic cancer (47 papers, 2008 to 2026). "Altered expression of Wnt5a has been implicated in human carcinogenesis and tumor progression, including that of pancreatic cancer." (PMID 33504014, 2021). "Recently, Wnt5a/Ror2 signaling has been implicated as an important pathway in epithelial-mesenchymal transition and promotion of invasion and metastasis in pancreatic cancer." (PMID 28427201, 2017). "Wnt5a is also associated with the strong desmoplastic reaction observed in pancreatic cancer." (PMID 35358569, 2022). "Here in our study, we found that a positive feedback loop between Wnt5a and Lin28b in pancreatic cancer cells." (PMID 37898598, 2023). "Wnt5a can promote the migration of pancreatic cancer cells by promoting paxillin phosphorylation through Wnt5a/JNK signaling." (PMID 37175948, 2023). "We next investigated the role of LINC01134 in regulating the WNT5A/WNT signaling pathway in pancreatic cancer." (PMID 37914721, 2023). "The continuous activation of the Wnt pathway and the overexpressions of canonical Wnt ligands (Wnt2, Wnt5a, and Wnt7a’s) are also observed in pancreatic cancer." (PMID 35686109, 2022). "Increased expression of canonical Wnt ligands, such as Wnt2, Wnt5a, and Wnt7a’s, have been observed in pancreatic cancer tissues, along with persistent activation of the Wnt pathway, leading to cancer progression." (PMID 31480221, 2019). "Wnt5a-dependent β-catenin signaling was shown to facilitate metastasis in pancreatic cancer and melanoma, but, in other cancers, it was shown to have contrasting results." (PMID 31480221, 2019). "Wnt5a mediates resistance to gemcitabine in pancreatic cancer cell lines by inducing a transcriptional signaling cascade dependent on NFATc2 in this study." (PMID 31480221, 2019). "A recent study using WNT5A knockdown showed an increase of cells in G0/G1 phase and a decreased cell number in S phase, which enhanced the chemosensitivity of pancreatic cancer cells to gemcitabine." (PMID 29882812, 2018). "Another study reported that WNT5A contributed to drug-resistance by enhancing anti-apoptosis ability in pancreatic cancer cells." (PMID 29882812, 2018). "Based on the conclusion that the effects of Wnt5a on promoting EMT and metastasis of pancreatic cancer cells, cellular processes of pancreatic cancer are associated with the activation of β-catenin-dependent canonical Wnt signaling." (PMID 29054966, 2017). "Using an orthotopic pancreatic cancer model, researchers demonstrated that Wnt5a-overexpressing cancer cells formed metastatic tumors at multiple sites, whereas control cells failed to metastasize." (PMID 29054966, 2017). "TGF-β has also been shown to induce WNT-5A expression in mammary glands, primary fibroblasts, primary epithelial cells, and pancreatic cancer cells." (PMID 26514730, 2016). "For example, Wnt5a signals through the transcription factor nuclear factor of activated T-cell C2 (NFATc2) to induce gemcitabine resistance and cell survival in pancreatic cancer in both in vivo and in vitro models." (PMID 27571105, 2016). "All the results of our experiment confirmed that WNT5a is active after co-culture with pancreatic cancer cells and has an autocrine and paracrine function, activating the c-JUN/AP1 pathway also in 3T3-L1." (PMID 26958939, 2016). "In pancreatic cancer, WNT5a is recurrently over-expressed and exerts a pro-oncogenic function by promoting proliferation, migration and invasion of cancer cells." (PMID 26958939, 2016). "It has been previously shown that Wnt5A, JNK and paxillin are overexpressed in pancreatic cancer and Wnt5A/JNK signaling stimulates cell migration in pancreatic cancer by activating paxillin." (PMID 26980710, 2016). "WNT5A expression was also found augmented in vivo, in the stroma from pancreas cancers and in fibroblasts surrounding both cutaneous SCC and BCC cells." (PMID 26694869, 2015). "CUTL1 drives WNT-5A expression in pancreatic cancer cell lines whereas TCF4 is the most common transcriptional partner of β-catenin." (PMID 24728340, 2014).
pancreatic cancer (continued). "In line with this, Wnt5a up-regulation was significantly shown to enhance migration, proliferation, and invasiveness in pancreatic cancer cells in vitro." (PMID 24405831, 2014). "Wnt5A and NFATc2 were also upregulated in expression in pancreatic cancer; inhibition of Wnt5A led to significant increases in drug induced apoptosis both in vitro and in vivo." (PMID 25401518, 2014). "It has been documented that Wnt5a is upregulated during pancreatic carcinogenesis and mediates the migration and invasion of pancreatic cancer cells induced by the transcription factor CUTL1." (PMID 24156409, 2013). "The scratch assay revealed that the percentage of wound closure at 24 h was significantly (P < 0.05) higher in Wnt5a-overexpressing pancreatic cancer cells than in empty vector-transfected cells." (PMID 24156409, 2013). "Using an orthotopic pancreatic cancer model, we demonstrated that Wnt5a-overexpressing cancer cells formed metastatic tumors at multiple sites, whereas control cells failed to metastasize." (PMID 24156409, 2013). "In conclusion, our data confirm an upregulation of Wnt5a in pancreatic cancer, especially well-differentiated carcinomas." (PMID 24156409, 2013). "The prognostic significance of Wnt5a expression in pancreatic cancer was evaluated using the Kaplan-Meier survival curve analysis." (PMID 24156409, 2013). "The percentage of Wnt5a positive expression showed a bell-shaped pattern in pancreatic cancer tissues, peaking in well-differentiated carcinomas." (PMID 24156409, 2013). "Overexpression of Wnt5a promoted the migration and invasion of pancreatic cancer cells, whereas Wnt5a depletion had an inhibitory effect." (PMID 24156409, 2013). "The induction of EMT was further confirmed in pancreatic cancer cells transfected with Wnt5a-expressing plasmids." (PMID 24156409, 2013). "The aim of this study was to determine the expression pattern, clinical significance, and biological functions of Wnt5a in pancreatic cancer." (PMID 24156409, 2013). "Our data demonstrated that enforced expression of Wnt5a resulted in increased snail protein expression in pancreatic cancer cells, suggesting an involvement of snail in Wnt5a-induced EMT of pancreatic cancer cells." (PMID 24156409, 2013). "Using an orthotopic mouse model of pancreatic cancer, we further assessed the effect of Wnt5a on pancreatic cancer invasion and metastasis in vivo." (PMID 24156409, 2013). "The aim of this study was to determine the expression pattern and clinical significance of Wnt5a in pancreatic cancer and clarify how Wnt5a contributed to aggressive phenotypes of pancreatic cancer cells." (PMID 24156409, 2013). "Regarding the expression extensity in pancreatic cancer tissues, Wnt5a showed a bell-shaped expression pattern with a significant peak in well-differentiated carcinomas." (PMID 24156409, 2013). "In an orthotopic pancreatic cancer mouse model, Wnt5a overexpression resulted in increased invasiveness and metastasis, coupled with induction of EMT in tumor cells." (PMID 24156409, 2013). "In vitro studies further confirmed the induction of EMT in pancreatic cancer cells by Wnt5a, as evidenced by increased expression of vimentin and reduced expression of E-cadherin." (PMID 24156409, 2013). "Taken together, the Wnt5a protein expression exhibited a bell-shaped pattern in human pancreatic cancer tissues." (PMID 24156409, 2013). "Western blot analysis further confirmed that Wnt5a-overexpressing pancreatic cancer cells undergo an EMT, as evidenced by an increase in the expression of vimentin and snail and a concomitant reduction in the E-cadherin expression." (PMID 24156409, 2013). "Our data confirm the previous finding that there is an elevation in Wnt5a expression in pancreatic cancer tissues compared to normal pancreatic tissues." (PMID 24156409, 2013). "Similarly, human MiaPaCa2 pancreatic cancer cells release Wnt5a, leading to adipocyte dedifferentiation." (PMID 39719444, 2024).